ZAP70 (zeta chain of T cell receptor associated protein kinase 70)
Diseases named in the same sentence as ZAP70 in open-access papers (continued):
Sharing a sentence is not in itself a finding about the gene and the disease.
infection (24 papers, 2013 to 2025). The state of being infected such as from the introduction of a foreign agent such as serum, vaccine, antigenic substance or organism. "OTUD7B (Cezanne) prevents tumor necrosis factor (TNF)-induced apoptosis of dendric cells in infection and facilitates T cell activation and inflammatory responses by regulating Zap70 ubiquitination." (PMID 39985644, 2025). "Patients with recurrent infection, combined with autoimmune or malignancy, especially those with selective CD8 + T cell loss, should be screened for ZAP-70 deficiency." (PMID 37101133, 2023). "Reduced levels of ZAP70 were observed at 6 hpi for both viruses, which were maintained until 24 hpi after infection with Estonia 2014, but dropped below detection levels in Armenia 2008-infected moMΦ at the later time point." (PMID 36298696, 2022). "Cell fractionation showed that pH1N1 infection caused increased accumulation of CD28 and Zap-70 proteins in plasma membrane in J1.1 cells." (PMID 26848681, 2016). "This suggests that disruption of Syk/ZAP70 signaling by CyaA impairs a broad range of processes that play a crucial role in host defense against infection." (PMID 26650353, 2015). "The infection also activated the ZAP70/NF-κB pathway, essential for peripheral Th1 differentiation, as evidenced by p65 nuclear translocation and significant upregulation of Th1-related genes, including those of the transcription factor Tbx21 and interleukin-12 receptors." (PMID 40170858, 2025). "Immunohistochemistry (using cross-reacting anti-Zap70 antibodies) along with BrdU immunolabelling indicated that local proliferation of T cells likely did not cause the increase in T cells observed at the infection site, supporting T cell migration." (PMID 34603313, 2021). "Significantly downregulated of key components of TCR and BCR signaling pathways, such as ZAP70, BTK, and CD79A, suggested a temporary inhibition of these pathways critical for cellular immunity post-infection." (PMID 39650642, 2024). "DEGs indicating positive activation of CD8+ cells, such as ZAP70 or LAT, were overexpressed at day 7pi, which suggests that CD8+ T cells are responding to the infection." (PMID 37920474, 2023). "Following infection by different pathogens, NELO underwent structural changes involving the formation of ZAP70+ cell clusters, suggesting direct involvement in immune responses." (PMID 37910624, 2023). "Infection with either strain increased expression of ISGs (GBP1, IFIT1, IRF7) and reduced expression of lymphocyte related genes (CD3D, CD8A, ZAP70)." (PMID 28852031, 2017). "Infection with wt EBOV resulted in the increase in phosphorylation of Lck; however, phosphorylation of additional adapters including ZAP70, PLCγ1 and SLP76 appeared to be blocked." (PMID 27930745, 2016). "We have perturbed the concentrations of the signaling molecules, viz., ZAP70, LCK and FYN, which are responsible for stimulating the TCR signaling pathway upon infection." (PMID 24324645, 2013). "T/NK cells have not been described as targets for SVCV and we did not observe infection of ZAP70+ cells by the virus." (PMID 34880866, 2021). "After infection, MP antigens stimulate and upregulate T cell surface molecules including CD3D, CD3E, CD3G, and CD8, followed by the upregulation of downstream molecules including CD3Z, FYN, LCK, ZAP70, GADS, P38, and ITK." (PMID 29967623, 2018). "In addition, we found that phosphorylation of CD3ζ (Tyr83), ZAP70 (Tyr319), and STAT1 (Ser727), as well as the expression of T-bet, was reduced in lung CD4+ T cells of CD4–TREM-2 KO mice upon MHV-A59 infection." (PMID 34878838, 2021). "Unexpectedly, infection with EBOV/VP24m resulted in an increase in the relative amount of phosphorylated ZAP70 despite the lack of phosphorylation of the downstream signaling molecules PLCγ1 and SLP76; however, this is consistent with the lack of effective T cell activation by this mutant." (PMID 27930745, 2016).
infection (continued). "A polyclonal antibody to zfCD4-1 was developed and used with an antibody to ZAP70 and revealed double positive cells by immunohistochemistry, and in the Mycobacterium marinum disease model CD4-1+ cells were apparent surrounding the granulomas typical of the infection." (PMID 26083432, 2015). "Furthermore, the investigation of downstream genes implicated in BCR signal transduction, including syk, btk, akt, blyk, lyn, p38, CD79a/b, ZAP-70, RAS, etc., exhibited no changes in expression in response to the SAV3 infection." (PMID 39691715, 2024).
adenocarcinoma (1 paper, 2025). A common cancer characterized by the presence of malignant glandular cells. "In regards to 11 kinases specifically regulated in AD, siRNA‐mediated gene‐silencing of CDK1, EPHA1, JAK3, RET and ZAP70 caused loss of cell viability in a panel of six human adenocarcinoma cell lines." (PMID 39995112, 2025).
hematopoietic cancers (1 paper, 2024). "In 3 independent studies, ZAP70, FYN, GRAP2, ITK, and CD247 (encoding CD3ζ) were highly upregulated in patients with T-ALL compared with individuals acting as healthy controls or people with other hematopoietic cancers, similar to our murine study." (PMID 38618957, 2024). "Furthermore, we found that expression levels of ZAP70, FYN, GRAP2, ITK, and LCK as well as two further TCR pathway kinases, PLCG1 and LAT, were highest in human T-ALL cell lines compared with other hematopoietic cancer lines." (PMID 38618957, 2024).
neurodegenerative disease (1 paper, 2015). A disorder of the central nervous system characterized by gradual and progressive loss of neural tissue and neurologic function. "Instead, together with the five upstream signalling factors (IGF1, BDNF, ZAP70, MYC, and cyclosporin A) they could help uncover the molecular mechanisms mediating AD or different neurodegenerative diseases." (PMID 26059363, 2015).
ZAP70 also shares sentences with these, for which no sentence is quoted: combined immunodeficiency (9 papers); chronic myeloid leukemia (3); multiple myeloma (3); Splenomegaly (3); Wiskott-Aldrich syndrome (3); allergies (2); colorectal cancer (2); enteropathy (2); inflammatory bowel disease (2); mastitis (2); T cell lymphoma (2); acute myeloid leukemia (1); antibody deficiency (1); ARTEMIS deficiency (1); autism (1); bacteremia (1); cholangiocarcinoma (1); Cirrhosis (1); CNS tumors (1); colon cancer (1); common variable immunodeficiency (1); coronary heart disease (1); diabetes (1); diffuse large B-cell lymphoma (1); DiGeorge syndrome (1); dilated cardiomyopathy (1); Emanuel syndrome (1); endocervical adenocarcinoma (1); endometriosis (1); enteritis (1).
A further 34 diseases each share a sentence with ZAP70 in 1 paper.